CRP (C-reactive protein)
Diseases named in the same sentence as CRP in open-access papers (continued):
Sharing a sentence is not in itself a finding about the gene and the disease.
Obesity (continued). "The condition of obesity is characterized by chronic low-grade inflammation with over-expression of inflammatory molecules and markers, such as C-reactive protein (CRP), interleukin 1 (IL-1), and interleukin-6 (IL-6)." (PMID 36615820, 2022). "In contrast, the median prepartum CRP concentration in the present study was considerably lower (3.3 mg/L), possibly owing to the low percentage of women with prepregnancy overweight or obesity." (PMID 35768766, 2022). "In our study, adiponectin was inversely related to CRP in obesity, but, surprisingly, leptin was inversely related to CRP in normal-weight patients." (PMID 36428528, 2022). "Increased muscle strength in obesity has also been associated with a better prognosis.In this evaluation of the obesity paradox, BMI is a protective factor in both lower and higher CRP groups." (PMID 36299943, 2022). "Since there are differences in fat distribution between men and women, the relationship between obesity and CRP also differs." (PMID 36304737, 2022). "Correlations between CRP and BMI in all groups suggest that overweight and obesity increase the intensity of inflammation and potentiate CD5L expression." (PMID 36556186, 2022). "The effect of Infliximab as an adjunct to TAU with a variety of medications was explored in a study performed in 60 patients with bipolar depression and evidence of inflammation (CRP>5, obesity, DM, IBD or rheumatological disorder)." (PMID 36217374, 2022). "Despite the effects of rising indicators of obesity, levels of CRP among Adult Migrants and Child Migrants >8, on average, were never as high as those among the second-generation British-Bangladeshis and Child Migrants ≤8." (PMID 35035976, 2022). "Further elevated circulating maternal IL-6 and CRP levels have been reported in pregnant women with obesity." (PMID 35348641, 2022). "The participants were also sufficiently young that it would be difficult to predict longer-term effects of obesity on CRP levels." (PMID 35035976, 2022). "This study aimed to evaluate effects of Probio-Tec ®BG-VCap-6.5 and magnesium co-supplementation on mood, cognition, intestinal barrier function and serum C reactive protein (CRP) levels in participants with obesity and depressed mood." (PMID 36245482, 2022). "We provide novel findings regarding the potential mediating role of inflammation on the obesity-poor PF relationship, with approximately 23% of the obesity effect operating via a downstream effect on CRP." (PMID 35301057, 2022). "Increased levels of IL-6, CRP and TNF-α are present in children with obesity, which increases atherosclerotic risk factors." (PMID 36292751, 2022). "CRP is a pro-inflammatory marker secreted by the liver whose levels have been reported to be elevated during obesity." (PMID 35624723, 2022). "We have previously shown that rats with high-fat diet-induced obesity and IR develop cardiac hypertrophy and elevated CRP levels in serum." (PMID 35620114, 2022). "For example, one observational study reported an inverse relationship between dietary magnesium intake and inflammatory parameter levels (in particular C-reactive protein, CRP) in people affected by obesity." (PMID 35277037, 2022). "Comparable to serum CRP and insulin, higher salivary CRP and insulin OR 4.94 [95%CI: 1.66,14., OR 2.64 [95%CI: 1.09, 6.38], respectively) were predictive of hyperglycemia and obesity (OR 4.53 [95%CI: 2.40,8.50], OR 3.29 [95%CI: 1.82,5.97], respectively)." (PMID 35757631, 2022). "Upregulation of CRP is considered a marker of systemic inflammation in autoimmune conditions, infection, and obesity." (PMID 35054785, 2022).
Obesity (continued). "Various studies suggest a tight link between obesity and high CRP serum levels, which not only contributes to an exacerbation of the systemic inflammatory state, but also suggests that an increase in serum levels of CRP has an inflammatory effect on obesity." (PMID 34835964, 2021). "The proportion of participants with Leptin and CRP levels in the fourth quartile was highest among those with obesity." (PMID 33680494, 2021). "It is interesting to note how, in different clinical settings, including psoriasis, hidradenitis suppurativa, obesity, and polycystic ovary syndrome, showed a strong relationship between PhA and inflammatory markers, including C-reactive protein." (PMID 33902622, 2021). "Since obesity is characterized by changes in metabolic profile and chronic low-grade inflammation, we first measured plasma levels of IL-6, CRP, and metabolic hormones." (PMID 34195568, 2021). "Linear regression and logistic regression analyses were used to compare the clinical parameters according to ASM%, adjusted for age, sex, obesity, hypertension (HT), DM, dyslipidemia (DL), smoking, alcohol intake, and C-reactive protein (CRP)." (PMID 33739984, 2021). "Generally, for all SLE patients, HC and the ‘SLE subgroup’ we observed a positive and mostly significant correlation of obesity (BMI) with leptin and CRP, in HC and the ‘SLE subgroup’ additionally between BMI and LPS levels." (PMID 34335609, 2021). "After adjustment for age, sex, HT, DM, DL, smoking, alcohol intake, and CRP, ORs remained significant for obesity, visceral adiposity, and sarcopenia (adjusted OR = 4.235, 3.552, and 3.674, respectively)." (PMID 34403431, 2021). "Other risk factors also include high levels of C-reactive protein (CRP), lipoprotein-A, haemoglobin A1c (HbA1c), obesity, family history of CHD, and others." (PMID 34627379, 2021). "After adjustment for age, sex, obesity, DM, HT, DL, smoking, alcohol intake and CRP levels, the OR of severe MetS with 5 criteria in subjects with sarcopenia was 3.119, which was higher than the 2.266 in the original MetS." (PMID 33739984, 2021). "Adipose tissue in obesity is characterized by higher levels of the proinflammatory cytokines, adipokines, and C-reactive protein (CRP), and lower levels of the anti-inflammatory and modulatory proteins such as adiponectin." (PMID 34436472, 2021). "Quantile regression was performed across the entire conditional distribution of CRP to illustrate the different impact of obesity (BMI ≥ 30 kg/m2) on the covariates." (PMID 32827080, 2021). "Obesity produces a marginal increase in the levels of the C-reactive protein and inflammatory factors that disturbs the insulin sensitivity in diverse organs, such as the pancreas, liver, heart, brain, and tissues like the adipose tissue and skeletal muscle." (PMID 34829598, 2021). "When admission factors including community-acquired AKI were included in the stepwise regression, admission oxygen saturations, respiratory rate and CRP became significant while obesity fell out of the model." (PMID 34301204, 2021). "Periodontitis and overweight or obesity independently change serum levels of leptin, adiponectin, and C-reactive protein (CRP)." (PMID 33603787, 2021). "This is consistent with other studies that reported an increase in CRP in response to an increasing in obesity indices." (PMID 33914792, 2021). "The mean concentrations for leptin and CRP were higher in participants with overweight/obesity compared to participants who were underweight/normal weight (7.9 ± 5.9 ng/ml vs. 3.5 ± 4.7 ng/ml and 0.33 ± 0.6 μg/ml vs. 0.14 ± 0.4 μg/ml, respectively)." (PMID 33680494, 2021). "It has been proven that obesity, previous vascular disease, increased high-sensitivity C-reactive protein levels, and optimal initial intraoperative blood flow (IOBF) < 190 ml/min are reasons for failed maturation." (PMID 33824829, 2021).
Obesity (continued). "Studies have confirmed that insufficient sleep is associated with increases in tumor necrosis factor, interleukin 6 and C-reactive protein, which play important roles in obesity." (PMID 34952580, 2021). "Hs-CRP was significantly correlated with BMI, in agreement with previous studies on the roles of CRP in weight and obesity." (PMID 33497355, 2021). "In the context of the obesity burden in Qatar, it is important to assess the iron status and include the measurement of inflammatory biomarkers (CRP or high-sensitivity CRP)." (PMID 33914792, 2021). "After adjusting for multiple confounders, including age, sex, HT, DM, DL, smoking, alcohol intake, and CRP levels, subjects with obesity, visceral adiposity, and sarcopenia were found to be associated with an increased risk for MS." (PMID 34403431, 2021). "The OR of MetS in participants with sarcopenia reached 2.266 after adjustment for age, sex, obesity, DM, HT, DL, smoking, alcohol intake and CRP levels." (PMID 33739984, 2021). "This was mainly based on the observations that C-reactive protein (CPR) and interleukin-6 (IL-6) levels were increased in obesity, and that weight loss was associated with a decline in cytokine levels." (PMID 33604566, 2021). "Out of all the comorbidities, only obesity positively correlated with peak levels of C-reactive protein (CRP)." (PMID 34178545, 2021). "Obesity is characterized by systemic inflammation and this is reflected in higher levels of CRP, which is closely related to total body fat." (PMID 32827080, 2021). "CRP has been used as a marker for obesity‐related low‐grade inflammation, which contributes to insulin resistance." (PMID 33680494, 2021). "We found out that patients with IBS, prevailing diarrhea and comorbid obesity develop a higher intensity of systemic inflammation, which was characterized by a high level of CRP in the blood serum and fibrinogen level." (PMID 34621378, 2021). "Participants with obesity presented with higher levels of CRP and oxidative DNA damage (8-OHdG) in urine, and lower levels of vitamin D in saliva." (PMID 34158611, 2021). "For example, C-reactive protein (CRP) is an important clinical indicator of inflammation, but studies have found that elevated CRP occurs in only 30-60% of adults with obesity." (PMID 34421889, 2021). "A meta-analysis showed beneficial effects of exercise on the inflammatory status (CRP and interleukin-6) in adults with obesity." (PMID 34485407, 2021). "Obesity-induced chronic inflammation has been detected in obesity-induced IR, and some inflammatory cytokines such as CRP, IL-6, TNF-α, and MCP1 are found in obesity-induced IR." (PMID 33781239, 2021). "CRP as a measure for low-grade systemic inflammation in obesity showed a trend to a positive correlation with pro-inflammatory intestinal macrophage subpopulation P2 in the stomach (p=0.08) and the duodenum (p=0.06)." (PMID 34054838, 2021). "This is generally due to the chronic pro-inflammatory state of patients with obesity, which results in an increase in acute-phase proteins such as CRP, as well as a decrease in albumin concentrations, both of which are clinical markers of inflammation." (PMID 35010957, 2021). "CRP (C-reactive Protein) and TNF alpha, two inflammatory markers commonly associated with low grade inflammation in obesity, were significantly lower in the IP group versus CP group (p < 0.05 and p < 0.01 respectively)." (PMID 34341379, 2021). "The chronic low-grade inflammatory state in obesity has been confirmed by high baseline CRP in overweight individuals." (PMID 33995281, 2021). "Several studies have found significantly higher serum CRP from children with obesity compared to controls, but results in saliva are so far limited and inconclusive." (PMID 34158611, 2021). "In the secondary outcome, obesity was the only patient characteristic that significantly correlated with peak-CRP levels." (PMID 34178545, 2021).
Obesity (continued). "Indeed, it has been reported that there is a higher incidence of metabolically healthy obesity in adolescents than adults and that adolescents require a relatively smaller amount of weight loss which results in changes in circulating inflammatory markers such as adiponectin and CRP." (PMID 34281497, 2021). "In line with the alterations detected in the redox homeostasis, increased plasma inflammation was also observed, in the children with obesity, in particular CRP and leptin levels." (PMID 34457110, 2021). "Among these associations, multivariable analysis confirmed those of HDL-C with age, obesity, disease duration and CRP." (PMID 34680168, 2021). "aDyspnea (P=0.041) and obesity (P=0.031), blog(CRP), cobesity (P=0.025) and D-dimer (P=0.039), and dlog(CRP) were also significant independent variables." (PMID 34878066, 2021). "At baseline, men with vitamin D deficiency had a more adverse health profile including the highest prevalence of smoking, heavy drinking, physical inactivity, obesity, hypertension and the highest mean CRP and IL-6 (markers of inflammation)." (PMID 34933860, 2021). "Pregravid obesity is marked by elevated circulating levels of inflammatory mediators C-reactive protein (CRP) and IL-6, subclinical endotoxemia, and signs of heightened inflammation in the adipose tissue compartment." (PMID 34195568, 2021). "Nevertheless, telomeres were negatively affected by obesity indices, such as BMI and WC, and inflammatory biomarkers CRP and homocysteine." (PMID 34769797, 2021). "In our exploratory analyses to examine the relationships between the gut microbiome and inflammation, we found that taxonomic α-diversity (overall Shannon diversity) reduced with increases in CRP in children with obesity." (PMID 34361925, 2021). "Prior to ω-3PUFA supplementation, plasma levels of inflammatory markers including CRP confirmed the presence of systemic inflammation in the setting of obesity and insulin resistance." (PMID 33753887, 2021). "CRP, a commonly used biomarker of meta-inflammation, has recently been included among criteria to define the obesity phenotypes." (PMID 34836180, 2021). "Among adipokines, leptin positively correlated with age, CV history, obesity, disease activity, CRP, IMT, and PWV." (PMID 34680168, 2021). "Second, the study sample of DNAm was selected based on obesity and T2D case-control status, which can influence CRP levels." (PMID 34117263, 2021). "An important caveat in these studies, however, is that C-reactive protein (CRP) and IL-6, inflammatory markers commonly used to assess inflammatory status in these studies, are positively correlated with obesity." (PMID 33718419, 2021). "The “weight loss” group also showed decreased levels of APOE, C5, CRP, LBP, NEGR1, and PRSS3, which have all been positively associated with obesity, inflammation, and metabolic disorders (22, –, 26)." (PMID 34519531, 2021). "Circulating plasma levels of several immuno-modulatory peptides, including TNFα, IL-6, IL-8, IL-10, IL-18 and C-reactive protein, were found to be elevated in human obesity." (PMID 34571976, 2021). "These coefficients are higher when the independent variables, obesity, PD, and sex are regressed on increasing CRP levels." (PMID 32827080, 2021). "Vitamin D insufficiency increases C-reactive protein (CRP) level that has been linked to an increased risk of cardiovascular disease, obesity and MetS." (PMID 34784977, 2021). "We then determined the relationship between obesity (BMI ≥ 30) and pulmonary function, after stratifying by insulin resistance or CRP." (PMID 34272443, 2021). "Further, CRP can also be a substitute biomarker of low-grade inflammation related to obesity: Studies reported that CRP levels were significantly higher in obese individuals with OSA, compared to non-obese individuals with OSA." (PMID 33921787, 2021).
Obesity (continued). "Due to the common link of both C-reactive protein and fibrinogen to the interleukin-6 gene promoter, those confounding effects such as nutritional status or obesity also influence the C-reactive protein level." (PMID 33747971, 2021). "In particular, the first study found an association between adherence to a low glycaemic index diet and lower levels of CRP and IL-6 in females with obesity or overweight." (PMID 33503979, 2021). "Previous studies have used observational epidemiology to explore the effect of obesity on the plasma proteome: one study used mass spectrometry and found an increase in Complement Factors I, B and H and an increase in CRP." (PMID 34226637, 2021). "Our findings also confirm that the obesity-related increase in CRP is further enhanced by the presence of PCOS." (PMID 33800490, 2021). "Increased circulating adiponectin and C-reactive protein (CRP) levels precede the development of RA in patients with obesity." (PMID 33669910, 2021). "Patients with obesity exhibited increased circulating concentrations of CRP as compared to both groups with either normal weight or overweight (p < 0.001)." (PMID 33917063, 2021). "Circulating CRP levels were analyzed in 13 studies which included 561 participants with overweight or obesity and were involved in a training program." (PMID 34948868, 2021). "Circulating levels of these mediators, together with CRP, constitute relevant damage biomarkers connecting chronic metabolic diseases such as obesity and T2D with incident dementia or late-onset AD." (PMID 33967682, 2021). "Obesity was associated with lower FEV1, FVC, and higher FEV1/FVC ratio only in the highest insulin resistance/CRP tertile." (PMID 34272443, 2021). "We only analysed data of non-obese participants to remove the known confounding effect of obesity on CRP." (PMID 33800490, 2021). "Elevated interleukin-6, CRP, adipokines, cytokines, and interferons in obesity characterize a chronic low-grade inflammation." (PMID 34178545, 2021). "WHR and waist circumference are surrogate markers for adiposity, and CRP is only a short living measure of inflammation induced by obesity as well as by periodontal inflammation, whereas fibrinogen has a longer half-life." (PMID 32827080, 2021). "Risk factors for severe infection include obesity (body mass index [BMI] ≥ 28 kg/m2), type 2 diabetes, hypertension, elevated lactate dehydrogenase (LDH > 250 U/L), C-reactive protein (CRP > 10 mg/L), and albumin (ALB < 35 g/L)." (PMID 34200036, 2021). "The levels of serum fibrinogen and other acute phase reactants, such as TNF-α, IL-6, and CRP were demonstrated to be increased in obesity." (PMID 34176464, 2021). "Recent studies show that a blood level of CRP above 10 mg/dL is related to chronic conditions such as obesity and poor social conditions, because people with poor diet and a sedentary lifestyle due to poverty and illiteracy are more prone to CVDs." (PMID 34680097, 2021). "Biomarker assessment using high-sensitivity C-reactive protein plasma levels of greater than 2 mg/dL identified individuals with seemingly metabolically healthy obesity and low-grade inflammation who also derived microvascular benefit from weight loss surgery." (PMID 34251443, 2021). "Overall, women met the criteria of obesity (BMI > 30 kg/m2), had above normal systolic blood pressure, serum triglycerides and CRP, but mean HbA1c in the normal range." (PMID 34769624, 2021). "HDL-C positively correlated with age, CV history, disease duration, and IMT, while inversely with CRP and obesity." (PMID 34680168, 2021). "The four clinical variables (male sex, obesity, patent false lumen, and D-dimer level ≥ 14.5 μg/mL) and peak CRP level had comparable ROC curves." (PMID 34862435, 2021). "Our study also revealed that participants with obesity had a significantly higher level of C-reactive protein." (PMID 34272443, 2021).